SUCLG2 (succinate-CoA ligase GDP-forming subunit beta)
Description:
GTP-specific succinyl-CoA synthetase functions in the citric acid cycle (TCA), coupling the hydrolysis of succinyl-CoA to the synthesis of GTP and thus represents the only step of substrate-level phosphorylation in the TCA. The beta subunit provides nucleotide specificity of the enzyme and binds the substrate succinate, while the binding sites for coenzyme A and phosphate are found in the alpha subunit (By similarity). Also able to act as a GTP-specific itaconyl- and malyl-CoA synthetase.
Synonyms: G-SCS; GTPSCS; GBETA
Tractability: Small molecule: a structure with a bound ligand is known. Antibody: its Gene Ontology location is reachable by antibodies, with high confidence; the Human Protein Atlas places it where antibodies can reach. PROTAC: ubiquitination databases record sites on it; its protein half-life has been measured.
Target class: Enzyme; Ligase
Gene: Protein-coding gene on chromosome 3 (67,360,460 to 67,654,624, reverse strand). Ensembl gene ENSG00000172340.
Subcellular location: Mitochondrion
Subcellular location (Human Protein Atlas): Mitochondria; Plasma membrane
Pathways (Reactome):
Metabolism: Citric acid cycle (TCA cycle)
Metabolism of proteins: Mitochondrial protein degradation
Gene Ontology:
Molecular function: protein binding; succinate-CoA ligase (GDP-forming) activity; succinate-CoA ligase (ADP-forming) activity; ATP binding; catalytic activity; GTP binding; magnesium ion binding
Biological process: succinyl-CoA catabolic process; succinyl-CoA metabolic process; tricarboxylic acid cycle
Cellular component: mitochondrion; succinate-CoA ligase complex (GDP-forming); mitochondrial matrix; succinate-CoA ligase complex
Genetic constraint (gnomAD): Loss-of-function variants: 39 observed, 45.33 expected, observed/expected ratio (o/e) 0.86, 90% interval 0.67 to 1.12. The upper end of that interval is the gene's LOEUF score, 1.12, which puts it in group 4 of 6, group 1 being the genes least tolerant of losing a copy. Missense variants: 567 observed, 525.56 expected, observed/expected ratio (o/e) 1.08, 90% interval 1.01 to 1.16. Synonymous variants: 194 observed, 194.8 expected, observed/expected ratio (o/e) 1, 90% interval 0.88 to 1.12.
Homologues: Orthologues: macaque SUCLG2 (99% identical), rabbit SUCLG2 (96% identical), pig SUCLG2 (95% identical), mouse Suclg2 (93% identical), chimpanzee SUCLG2 (93% identical), rat Suclg2 (92% identical), dog SUCLG2 (89% identical), guinea pig SUCLG2 (89% identical), tropical clawed frog suclg2 (82% identical), zebrafish suclg2 (82% identical), Drosophila melanogaster ScsbetaG (55% identical), Caenorhabditis elegans sucg-1 (52% identical). Paralogues in human: SUCLA2 (51% identical).
Diseases named in the same sentence as SUCLG2 in open-access papers:
SUCLG2 is named in the same sentence as 65 diseases in open-access papers, as found by Europe PMC text mining. Sharing a sentence is not in itself a finding about the gene and the disease. The quoted sentences say what the papers report.
prostate carcinoma (7 papers, 2020 to 2025). A carcinoma that arises from epithelial cells of the prostate gland. "In prostate cancer cells, SUCLG2 enhances the succinic synthetase activity of mitochondrial nucleoside diphosphokinase and promotes leukemia suppressor receptor signaling to enhance prostate cancer aggressiveness." (PMID 40699864, 2025). "Among these genes, we found examples of proto-oncogenes that were downregulated, such as succinate-CoA ligase GDP-forming β subunit (SUCLG2), which is known to drive neuroendocrine differentiation of prostate cancer after androgen deprivation therapy." (PMID 39766901, 2024). "Furthermore, quantitative real-time polymerase chain reaction and immunofluorescence assays were performed to validate SUCLG2 expression in clinical samples and the prostate carcinoma epithelial cell line 22Rv1." (PMID 40747103, 2025). "The enrichment of SUCLG2 in both luminal and basal/intermediate cell subsets may suggest context-dependent roles in prostate cancer biology." (PMID 40747103, 2025). "Our model also predicts that GTP-specific beta subunit of succinyl-CoA synthetase (SUCLG2) is selectively lethal in malignant prostate cancer cells because the alternative route via ATP-specific succinyl-CoA synthetase (SUCLA2) is absent in the malignant model." (PMID 32103057, 2020).
colon cancer (6 papers, 2020 to 2025). "A significant link between SUCLG2 gene rs35494829 and colon cancer was observed [ORs (95% CIs) per increment for minor allele, 0.82 (0.74–0.92)]." (PMID 38186579, 2023). "Based on a population-level cohort study in UK, the genetic variants of the citric acid cycle was significantly associated with CRC, especially between the SUCLG2 gene rs35494829 and colon cancer." (PMID 37014438, 2023). "SUCLG2P2 is highly homologous with SUCLG2, and is associated with colon cancer stage, metastasis and survival." (PMID 34589110, 2021). "We found a significant association between the SUCLG2 gene rs35494829 and colon cancer (ORs [95% CIs] per increment of the minor allele, 0.82 [0.74–0.92])." (PMID 33053772, 2020). "We found the significant association between SUCLG2 rs35494829 and colon cancer (ORs [95% CIs] per increment of the minor allele, 0.82 [0.74–0.92])." (PMID 33053772, 2020). "It has been reported that rs35494829 of the SUCLG2 gene is associated with colon cancer." (PMID 34589110, 2021). "SUCLG2P2 downregulation alongside SUCLG2 in colon cancer implies a shared mechanism in carcinogenesis." (PMID 40556338, 2025). "In colon cancer, the expressions of SUCLG2 and SUCLG2P2 are reduced, the competitive binding hsa-miR-588 is reduced, hsa-miR-588 is increased, and hsa-miR-588 exerts a tumor suppressor effect." (PMID 34589110, 2021). "Association between SUCLG2P2, SUCLG2 and ATIC genes and clinicopathological parameters of colon cancer patients." (PMID 34589110, 2021). "When the expression of SUCLG2P2 decreases in colon cancer, the combined hsa-miR-588 decreases, which increases the binding of hsa-miR-588 to SUCLG2, which in turn leads to an increase in SUCLG2 degradation and a decrease in SUCLG2 expression." (PMID 34589110, 2021). "The expression of SUCLG2 was low in most tumors, especially in colon cancer." (PMID 34589110, 2021). "The pseudogene SUCLG2P2 along with two other genes (SUCLG2 and ATIC) were introduced as potential prognostic markers for colon cancer, aiding in predicting patient outcomes and tailoring treatment strategies." (PMID 40556338, 2025). "In conclusion, the expressions of SUCLG2P2, SUCLG2 and ATIC in colon cancer and normal tissues were different, and they were related to survival." (PMID 34589110, 2021).
glioma (5 papers, 2024 to 2025). A benign or malignant brain and spinal cord tumor that arises from glial cells (astrocytes, oligodendrocytes, ependymal cells). "This study revealed five genes associated with the prognosis of glioma (ECI2, MCCC2, OXCT1, SUCLG2, and CPT2), providing novel insights into individualized treatment and prognosis." (PMID 39491527, 2024). "Additionally, the Kaplan–Meier survival and correlation analyses indicated that elevated SUCLG2 expression levels were significantly positively correlated with poor overall survival rates in patients with glioma." (PMID 41249152, 2025). "We examined the SUCLG2 expression levels in 12 glioma tissue samples (four each from Grades II, III, and IV) and four samples of injured brain tissues using western blot analysis, real-time quantitative polymerase chain reaction (RT-qPCR), and immunohistochemistry (IHC)." (PMID 41249152, 2025). "Five genes associated with the prognosis of glioma (ECI2, MCCC2, OXCT1, SUCLG2, and CPT2) were revealed and then, validated using glioma tissues, providing novel insights into individualized treatment and prognosis." (PMID 39491527, 2024). "ECI2, MCCC2, OXCT1, SUCLG2, and CPT2 were identified as prognostic genes for glioma." (PMID 39491527, 2024).
colon adenocarcinoma (3 papers, 2021 to 2024). "Results showed increased expression of ENO3, MORC2, SUCLG2 and ELOVL6, and decreased expression of CPT2 in all examined colon adenocarcinoma cell lines." (PMID 36568396, 2022). "Moreover, qRT-PCR revealed upregulated expression of ENO3, MORC2, SUCLG2 and ELOVL6, and downregulated expression of CPT2 in all examined colon adenocarcinoma cell lines." (PMID 36568396, 2022). "While low expression of SUCLG2 (p < 0.001), PTGR1 (p = 0.001), ELOVL6 (p = 0.013) and CPT2 (p < 0.001) were correlated with poor overall survival of colon adenocarcinoma patients." (PMID 36568396, 2022).
colorectal cancer (3 papers, 2020 to 2026). A primary or metastatic malignant neoplasm that affects the colon or rectum. "To understand the clinical significance of SMOX and SUCLG2, we focused on colorectal cancer (CRC) for further analyses and predicted and constructed a potential competing endogenous RNA (ceRNA) network." (PMID 40699864, 2025).
glioblastoma (3 papers, 2021 to 2025). The most malignant astrocytic tumor (WHO grade IV). "Remarkably, SUCLG2 was reported downregulated also in KDM1A-silenced glioblastoma cells confirming a positive correlation between KDM1A and SUCLG2." (PMID 37385999, 2023). "The analysis revealed that the SUCLG2 expression was lower in most tumors compared to the normal tissues, but higher in glioblastoma." (PMID 34589110, 2021).
lung adenocarcinoma (3 papers, 2023 to 2025). A carcinoma that arises from the lung and is characterized by the presence of malignant glandular epithelial cells. "In contrast, loss of SUCLG2 increases the succinylation levels of mitochondrial proteins, which may compromise mitochondrial function in lung adenocarcinoma cells by diminishing enzymatic activity." (PMID 40865948, 2025). "SUCLG2 expression is markedly upregulated in lung adenocarcinoma (LUAD) tissues relative to adjacent normal counterparts." (PMID 40865948, 2025). "A recent study indicated that the deletion of SUCLG2 upregulates succinylation levels of mitochondrial proteins and inhibits the function of key metabolic enzymes, impairing mitochondrial function in lung adenocarcinoma cells." (PMID 40925894, 2025). "The high succinylation of SUCLG2 in lung adenocarcinoma is related to mitochondrial dysfunction and low survival rate of patients." (PMID 40865948, 2025). "Previous studies have indicated that SUCLG2 expression influences both the proliferative capacity and invasive behavior of lung adenocarcinoma cells." (PMID 40865948, 2025). "Here, it is demonstrated that the expression level of succinyl‐coenzyme A (CoA) synthetase GDP‐forming subunit β (SUCLG2) can affect the overall succinylation of lung adenocarcinoma (LUAD) cells." (PMID 37904651, 2023). "While this pathway is functional in normal cells, it is suppressed in lung adenocarcinoma cells due to reduced TRIM21 activity or expression, leading to SUCLG2 succinylation, increased stability, abnormal accumulation, and enhanced tumor cell proliferation." (PMID 40865948, 2025). "In the current study, we found that SUCLG2, but not SUCLA2, was overexpressed in lung adenocarcinoma (LUAD) and closely related to patients’ survival." (PMID 37904651, 2023).
lung carcinoma (2 papers, 2023 to 2025). "However, we did not observe similar correlation between the protein expression of SIRT5 and SUCLG2, like that between TRIM21 and SUCLG2, in lung cancer tissues and adjacent normal tissues." (PMID 37904651, 2023). "Furthermore, SUCLG2 expression was significantly elevated in various cancer tissues, including those of GBM, breast cancer, cholangiocarcinoma, bladder cancer, and lung cancer." (PMID 41249152, 2025). "However, the function and mechanism of SUCLG2 in lung cancer progression have not been studied." (PMID 37904651, 2023).
rectal cancer (2 papers, 2020 to 2021). A primary or metastatic malignant neoplasm that affects the rectum. "Abdominal obesity was significantly associated with rectal cancer among noncarriers of SUCLG2-rs35494829 (1.35 [1.12–1.63]), OGDHL-rs11101224 (1.37 [1.12–1.68]), and OGDHL-rs751595 (1.40 [1.14–1.72])." (PMID 33053772, 2020).
schizophrenia (2 papers, 2019 to 2024). A major psychotic disorder characterized by abnormalities in the perception or expression of reality. "In the TCA cycle, the genes CS, SDHA, and SUCLG2 were upregulated in schizophrenia but downregulated in ketosis, and SDHB was downregulated in both." (PMID 39125835, 2024).
acute kidney injury (1 paper, 2021). Sudden and sustained deterioration of the kidney function characterized by decreased glomerular filtration rate, increased serum creatinine or oliguria. "Moreover, cg07242931 in MAN1C1 and cg18194850 in SUCLG2 were not only associated with eGFR, but predicted time to kidney failure or acute kidney injury." (PMID 34887417, 2021).
adenoma (1 paper, 2021). A neoplasm arising from the epithelium. "The expression of HIGD1A exhibited a significant reduction in two subtypes of adenoma and six subtypes of CRC, while the down-regulation of SUCLG2 and SLC25A24 showed more advantages in rectal mucinous adenocarcinoma." (PMID 34174878, 2021).
Alzheimer disease (1 paper, 2021). A progressive, neurodegenerative disease characterized by loss of function and death of nerve cells in several areas of the brain leading to loss of cognitive function such as memory and language. "SUCLG2 plays an important role not only in neurometabolic disorders and Alzheimer’s disease, but also in tumors." (PMID 34589110, 2021).
cognitive decline (1 paper, 2016). "A gene described recently as SUCLG2 (Succinyl-CoA Ligase) appears to determine CSF Aβ levels and attenuate cognitive decline in AD." (PMID 27092308, 2016).
colorectal tumors (1 paper, 2021). "Next, to further understand the potentials of HIGD1A, SUCLG2, and SLC25A24 as the IPFs for CRC, we investigated their mRNA expression in unique datasets of CRC and different subtypes of colorectal tumors through the Oncomine database." (PMID 34174878, 2021).
follicular adenoma (1 paper, 2024). "SUCLG2 is estimated to be a biomarker candidate that can effectively differentiate between follicular adenoma and carcinoma with 75% sensitivity and 80% specificity, depending on a specific cutoff score extrapolated from the intensity and percentage of immunohistochemistry (IHC) staining." (PMID 38315203, 2024). "Moreover, the GDP-forming beta subunit of succinate-CoA ligase (SUCLG2) was recommended as a candidate biomarker to distinguish between follicular adenoma and follicular carcinoma." (PMID 38315203, 2024).
major depressive disorder (1 paper, 2024). An episode of depression lasting two or more weeks without an intervening episode of mania. "In the TCA cycle, CS, IDH3G, SDHA, and SDHB were upregulated in major depressive disorder and downregulated in ketosis, whereas SUCLG2 was downregulated in both." (PMID 39125835, 2024).
MELAS (1 paper, 2021). "The heterozygous mutation in SUCLG2, c.235G > T (p.Glu79*) has been identified in three MELAS patients (P1, P3 and P5)." (PMID 33484326, 2021).
mitochondrial DNA depletion syndrome (1 paper, 2019). The mitochondrial DNA (mtDNA) depletion syndrome (MDS) is a clinically heterogeneous group of mitochondrial disorders characterized by a reduction of the mtDNA copy number in affected tissues without mutations or rearrangements in the mtDNA. "The succinate-CoA ligase GDP-forming beta subunit (SUCLG2) has been implicated in the SUCLG1-related mitochondrial DNA depletion syndrome affecting brain and skeletal muscle tissues." (PMID 30606113, 2019).
Mitochondrial encephalopathy (1 paper, 2021). "Another patient P3 harbored variants in two genes namely POLG (p.Arg1187Trp) and SUCLG2 (p.Glu79*) reported to be associated with mitochondrial respiratory chain diseases and mtDNA depletion, impaired respiratory complex subunits and mitochondrial encephalopathy, respectively." (PMID 33484326, 2021).
neuroendocrine tumors (1 paper, 2023). "The latest advances in the known genetics of neuroendocrine tumors such as SUCLG2 (succinyl-CoA ligase ß Subunit G2, an oxygen-sensing domain in hypoxia inducible factor 2) and IDH2 (isocitrate dehydrogenase 2) were recently reported." (PMID 36936415, 2023).
rectal mucinous adenocarcinoma (1 paper, 2021). "This suggested that SUCLG2 and SLC25A24 might be used as helper genes for HIGD1A in clinical diagnosis, which might improve the diagnostic accuracy of rectal mucinous adenocarcinoma." (PMID 34174878, 2021).
Right ventricular cardiomyopathy (1 paper, 2020). Right ventricular dysfunction (global or regional) with functional and morphological right ventricular abnormalities, with or without left ventricular disease. "The pathways involved in the antagonistic GSK-126 group were the bacterial invasion of epithelial cell pathway and the arrhythmogenic right ventricular cardiomyopathy (ARVC) pathway, involving proteins of the PSMD family such as CTNNB1, CTNNA1, PHB1, and SUCLG2." (PMID 33195195, 2020).
Sepsis (1 paper, 2025). Sepsis is defined as life-threatening organ dysfunction caused by a dysregulated host response to infection. "Furthermore, an enzyme reported to synthesize lactyl-CoA, GTPSCS/SUCLG2 requires much higher levels of lactate (Km = 15.32 ± 1.28 mM) and may therefore only generate appreciable amounts of lactyl-CoA under extreme conditions like intense exercise, sepsis, or cancer." (PMID 40835008, 2025).
thyroid cancer (1 paper, 2025). "Therefore, it could be inferred that circPSD3 served as a miR-338-5p sponge, influencing the malignant characteristics of thyroid cancer through the modulation of SUCLG2 expression." (PMID 40925894, 2025).
viral infections (1 paper, 2022). "The 8-gene signature included three genes over-expressed in bacterial infections (SMARCD3, ICAM1, EBI3; “bacterial genes”) and five over-expressed in viral infections (JUP, SUCLG2, IFI27, FCER1A, HESX1; “viral genes”)." (PMID 36543117, 2022).